ENSG00000258320 (SURP and G patch domain containing 1 (SUGP1) pseudogene)
Synonyms: LOC100128674
Gene: Processed pseudogene on chromosome 12 (74,170,445 to 74,171,830, forward strand). Ensembl gene ENSG00000258320.
Diseases named in the same sentence as ENSG00000258320 in open-access papers:
ENSG00000258320 is named in the same sentence as 1 disease in open-access papers, as found by Europe PMC text mining. Sharing a sentence is not in itself a finding about the gene and the disease.
ENSG00000258320 shares sentences with these, for which no sentence is quoted: cancer (1 paper).